MYC (MYC proto-oncogene, bHLH transcription factor)
Diseases named in the same sentence as MYC in open-access papers (continued):
Sharing a sentence is not in itself a finding about the gene and the disease.
tumor (continued). "As a result, defects of the translation machinery alter the expression of tumor-promoting proteins like KRAS, mTOR and MYC which, in turn, directly affect transcription of several important RNAs and drive carcinogenesis." (PMID 33092114, 2020). "TPL-mediated disruption of cell-specific SEs to downregulate gene expression (MYC, BRD4, RNA Pol II, COL1A2, etc.), as elucidated here, implies its therapeutic relevance in targeting both stromal and tumor compartments of PDAC." (PMID 33168807, 2020). "As sphere formation reflects the self-renewal capacity of tumor cells, we analyzed stemness marker genes, SOX2, OCT4, NANOG, and c-MYC." (PMID 33276627, 2020). "We determined if MYC and TWIST1 in human tumors cooperated to influence the tumor microenvironment through CIBERSORT analysis of 10,366 tumors from the human pan-cancer TCGA study." (PMID 31933479, 2020). "By preventing PP2A-B56α interaction with MYC, CIP2A gained scientific attention, and it is now considered a promising target for tumor treatment, particularly in AML, where it is overexpressed and promotes cell growth and neoplastic transformation." (PMID 32110991, 2020). "We also included genes with well-established roles in cancer, including MYC (proto-oncogene), RB1 (tumor suppressor), and EIF4E (translation initiation factor), to contrast with the aaRS genes." (PMID 33266490, 2020). "We next investigated the importance of the c-MYC signaling pathway for ATL cells proliferation and tumor formation in vivo." (PMID 32907612, 2020). "BASP1 overexpression strongly interferes with MYC‐induced oncogenesis and the BASP1 protein displays properties of a tumor suppressor, also in human cancer." (PMID 31944520, 2020). "We found that MYC and TWIST1 drive metastasis by eliciting a transcriptional program in cancer cells that induces cytokines that in turn enable crosstalk between tumor and host, thus eliciting the recruitment and polarization of macrophages." (PMID 31933479, 2020). "MYC proteins play an important role in oncogenesis and progression of tumors and many reports have shown that suppression of MYC or MYCN by genetic means results in growth arrest, induction of apoptosis or senescence leading to tumor regression." (PMID 33585252, 2020). "A tumor-suppressive function is exerted by IGF2BP1 too, which inhibits KRAS, CDC34, and MYC expression and promotes apoptosis." (PMID 33238574, 2020). "By contrast, other studies demonstrated that co-amplified MYC and PVT1 cooperatively promote tumor progression." (PMID 32235890, 2020). "STAT3 is an important member of the STATs family and can regulate a variety of key tumor factors, including the anti-apoptotic gene BCL-2 and the cell cycle control gene c-MYC." (PMID 33746736, 2020). "(g) Representative images from IHC staining for MYC and F4/80 in MYC/Twist1 HCC in temporal sequence from early tumor (n = 5) to later tumor (n = 5) and tumor regression (n = 5) upon oncogene inactivation." (PMID 31933479, 2020). "Given the pivotal role of CDK7 in regulating the expression of genes involved in oncogenesis, stemness, tumor growth, and progression, we next determined the effect of CDK7 inhibition on the expression of MYC, STAT3, and β-catenin." (PMID 32340192, 2020). "(d) Serial cross sectional imaging of MYC- (n = 10) and MYC/Twist1-HCC (n = 10) using MRI scan for the abdomen and CT scan for the lungs demonstrate step-wise tumor progression." (PMID 31933479, 2020). "Interestingly, patients with high levels of tumor-associated caspase-4 but who were c-MyC negative (c-MyC−) still had lower survival rate (median survival = 2.036 years) (blue line), although it was higher than patients positive for both Caspase-4 and c-MyC (black line)." (PMID 33187551, 2020). "MYC transcription is under the regulation of Bromodomain-containing 4 (BRD4) and a BRD4 inhibitor, JQ1, was found to possess anti-tumor effects." (PMID 32748879, 2020).
tumor (continued). "The resulting mesenchymal tumoral cells are characterized by the depletion of the chromatin regulator SMARCB1 and by the consequent activation of MYC, eventually leading to increased protein anabolism and biomass synthesis." (PMID 32932943, 2020). "CNAs in MYC, CCNA1, and BIRC7 were significantly enriched in depressed neoplasms and designated as the D-marker panel." (PMID 32532105, 2020). "c-MYC has been founded an elevated expression in PCa and multiple studies shown c-MYC can induce tumor cells proliferation and regulate cell cycle though MYC-responsive genes 7, 23-25." (PMID 31956349, 2020). "In support of this notion we observed acquisition of tumor-specific SEs in proximity to known oncogenes such as EGFR and MYC, as well as a large number of genes whose role in TNBC has not yet been established." (PMID 32584896, 2020). "PCM4 inhibited the tumor growth of PDXs (T64, T69, T144, T123, T174, T169, and T156) with high TRIB3 and MYC expression compared with PDXs (T151, T1, and T3) with low TRIB3 and MYC expression." (PMID 33298911, 2020). "Fusion of BirA∗ to the MYC oncoprotein in cultured HEK293 and tumor xenografts confirmed known and identified over 70 new potential interaction partners, ranging from chromatin remodelers to transcription factors." (PMID 32477404, 2020). "The genes most frequently showing CNGs in HAS tumour tissues were TOP1 (50.0%), STK4 (45.5%), CDKN1B (40.9%), H3F3A (36.4%), MYC (22.7%), CCNE1 (22.7%), NFKBIA (22.7%), VEGFA (18.2%), CCND3 (13.6%), and E2F1 (13.6%)." (PMID 30989433, 2019). "The use of JQ1 is very promising in several c-MYC-amplified tumors in which the downregulation of c-MYC leads to cell cycle arrest and apoptosis, thus inhibiting hypoxia and tumor progression." (PMID 31040907, 2019). "In contrast, miR-34a has been identified as a tumor suppressor miRNA by repressing several target genes, such as cyclin-dependent kinase 4 (CDK4), CDK6, BCL2, MET, Notch, c-MYC, AXL and FOXP1." (PMID 31472685, 2019). "SPAG5 promoted tumor growth and decreased cell sensitivity to PARPi via the MYCBP/c-MYC pathway in TNBC." (PMID 30736840, 2019). "Rescue experiments established that the tumor suppressive activity of MKC8866 is, at least in part, due to inhibition of XBP1s-mediated c-MYC expression." (PMID 30679434, 2019). "Thus, the mechanism of coamplification of PVT1 and MYC in tumor cells may involve a positive feedback pathway in which c-Myc increases the transcription of PVT1 by binding to E-boxes located in the PVT1 promoter region, which results in the increased expression of PVT1." (PMID 31309249, 2019). "The most potent combination tested: MYC, BCL2, P53dd, and CCND3 resulted in tumor formation in all mice within 38 days." (PMID 31586074, 2019). "In some tumor types, TNF-α was shown to promote tumor cell migration and metastasis by inducing RAS or c-MYC activation and expression of MMPs (e.g. MMP-3 and 9)." (PMID 31600735, 2019). "As already alluded above, CSCs within the OSCC tumor nests co-express OCT4, SOX2, NANOG, phosphorylated STAT3 (pSTAT3), CD133, CD44, and c-MYC." (PMID 31861233, 2019). "They demonstrated that MYC expression correlates with the degree of responses to JQ1, HDAC, and vincristine, emerging as a potential tumor biomarker of T-ALL." (PMID 31226848, 2019). "At the transcriptomic level, tumours with high MYC mRNA and low ATM mRNA expressions had increased tumour size, ER− and PR− tumours (all adjusted p values ≤ 0.01)." (PMID 30746633, 2019). "Bridging integrator 1 (BIN1), also known as Myc box-dependent-interacting protein 1, was identified as a tumor suppressor interacting with MYC box 1, a highly conversed region of the c-MYC N terminus." (PMID 31496920, 2019). "Nuclear MYC and FOSL1 positivity in tumor cells was evaluated using a four-tiered scoring system (Section 4) and cases were classified as low (score 0–1) and high (score 2–3)." (PMID 31438567, 2019).
tumor (continued). "In compound mutant mice, overexpression of c-MYC in an immunodeficient background led to a decreased incidence of CPP and reduced tumour bulk." (PMID 31142360, 2019). "CycT also decreases the levels of two regulators promoting OXPHOS, MYC and MCL1, and effectively alleviates tumor hypoxia." (PMID 30723259, 2019). "MYC expression levels, as well as PTEN status and Ki67 expression in primary tumor samples are strong predictors of progression-free survival, more accurately than clinical factors." (PMID 31366128, 2019). "Increasing studies showed that the expression of let-7 in the tumor was downregulated and can inhibit the gene expression of HMGA2 and MYC at the transcriptional level." (PMID 31196036, 2019). "To further investigate the anti-tumor effect of JQ1 in a variety of HCC cells, we assessed the expression levels of BRD4 and MYC in ten HCC cell lines." (PMID 30770740, 2019). "Several studies have validated c-MYC as a therapeutic target, including transgenic mouse models where suppression of MYC expression resulted in tumor regression." (PMID 30906568, 2019). "We observed a similar anti-correlation of MYC and BCL2 protein levels in immunohistochemical (IHC) stainings of human SCLC tumor specimens (n = 48)." (PMID 31375684, 2019). "Here, we report that in T-ALL, the MYC oncogene controls the expression of both TET1 and TET2, which in turn contribute to tumor cell-specific 5mC and 5hmC patterns in a genome-wide fashion with importance for tumor maintenance." (PMID 31266538, 2019). "In our retrospective cohort, a significantly higher fraction of MYC+ and FOSL1+ tumor cells were detected in basal-type UBC compared to luminal-type." (PMID 31438567, 2019). "Gene ontology analysis of these DEGs showed that in advanced stage tumours, pathways such as cell adhesion (VCAN), ECM receptor interaction (COL1A2, COL3A1, ITGA11, and TNN) and pathways in cancer (JUN, and MYC) getting deregulated." (PMID 31292488, 2019). "As MKI67 and MYC are two famous driver oncogenes in carcinogenesis and tumor progression, the relationships between the expression levels of EPB41L4A-AS2, MKI67 and MYC were next explored." (PMID 30764831, 2019). "Among the most frequently altered metabolic regulators were PTEN (in 14% of all tumours), KRAS (in 11%) and MYC (in 11%)." (PMID 31754644, 2019). "One of the important roles of MYC is regulation of L-neutral amino acid transporter 1 (LAT1) protein and inhibition of LAT1 would provide similar anti-tumor effect." (PMID 31601917, 2019). "MAX-independent expression of MYC in MM and its precursors requires further investigation; a recent abstract identified MAX as a tumor suppressor driver gene in MM, which is a promising start." (PMID 31156714, 2019). "If the “promoter–enhancer competition” between PVT1 and MYC commonly exists in cells, the PVT1 promoter serves as a tumor suppressor, and will further downregulate the expression of MYC, preventing the development of MYC-driven tumors." (PMID 31309249, 2019). "This study has shown that UNR/CSDE1 is involved in the malignant phenotype of tumor cells by regulation of EMT and c-MYC expression." (PMID 31027221, 2019). "c-MYC is observed to be frequently amplified in NSCLC, promoting various kinds of tumor malignant behaviors such as proliferation, invasion, chemotherapy resistance and immune escape." (PMID 31496920, 2019). "FBXW7 is a ubiquitin ligase and known to function as a tumor suppressor regulating NOTCH, MYC, and other oncogenes." (PMID 30709382, 2019).
tumor (continued). "It was shown that c-MYC recruitment to the E-box in the URI1 promoter region was significantly increased in HCC-B tumor tissues, compared with paired non-tumor liver tissues, suggesting that c-MYC is involved in the transcription of the URI1 gene in HCC-B." (PMID 31739577, 2019). "IHC staining of the excised tumor sections showed that the expression of Ki-67, which was consistent with that of IGF2BP2 and MYC, decreased with the depletion of LINRIS." (PMID 31791342, 2019). "The abnormal expression of miR-105 in EV is the result of the MYC oncoprotein in BC cells and in turn, acts on MXI1 in CAFs and activates MYC signaling to induce a metabolic program that is suitable for tumor growth." (PMID 31281797, 2019). "Intratumoral genetic heterogeneity of c-MYC GCN gain, which was arbitrarily defined as the tumor cells with c-MYC GCN ≥ 4.0, consisted 5 to 50%." (PMID 30733532, 2019). "Studies have shown that the high expression and amplification of the MYC gene can promote tumor metastasis, which is closely related to the epithelial–mesenchymal transition (EMT) of tumor cells." (PMID 31309249, 2019). "Downregulated pathways contained MYC-, MTORC1 signaling, and glycolysis—in line with the proposed role of STAT5 in tumor formation." (PMID 30679796, 2019). "We recently described, in a cohort of 55 Patient-derived tumor xenografts (PDTX) from PDAC patients two subgroups of PDAC patients, named MYC-high and MYC-low." (PMID 31231611, 2019). "The merged immunofluorescent-staining of MYC and PRMT5 demonstrated a significant co-localization pattern in both HD-MB03 and primary tumor cells." (PMID 31694585, 2019). "Considering that ZFHX3 is necessary for ERβ to repress MYC transcription, it is reasonable to propose that ERβ also depends on ZFHX3 to exert its tumor suppressor activity." (PMID 30979864, 2019). "Alteration of m6A levels participates in cancer pathogenesis and development via regulating expression of tumor-related genes like BRD4, MYC, SOCS2 and EGFR." (PMID 31801551, 2019). "When the cells with c-MYC GCN ≥ 4.0 were less than 5% or more than 50%, the tumor was considered genetically homogenous in terms of c-MYC GCN." (PMID 30733532, 2019). "Transcriptome analyses showed that TSPX or TSPX[∆C] overexpression downregulated multiple cancer-drivers/oncogenes, including MYC and MYB, in a CAD-dependent manner and upregulated various tumor suppressors in a CAD-independent manner." (PMID 30863497, 2019). "We concluded that XPO1 suppression abrogates the function of MYC oncogene and induces mass apoptosis in DHL tumor cells." (PMID 31752970, 2019). "MYC, a master regulator of transcription, activates Ras/ERK proliferative pathways while CDK4 and CCDN1 contribute to tumor advancement by promoting of G1 phase of cell cycle in CRC." (PMID 31409279, 2019). "Anti-cancer effects of tumour regression and the suppression of p-AKT and MYC was observed in K-RAS-driven LC mouse models through the administration of combination therapy of SMAPs (DT-061) and MEK inhibitor, AZD6244." (PMID 31623614, 2019). "Of the seven remaining ALT-negative tumors that lacked TERT rearrangement, one tumor harbored amplification of MYC, a known transcriptional activator of TERT31, and this tumor displayed elevated TERT expression (arrow)." (PMID 29802247, 2018). "We next investigated if ALK is involved in transcriptional regulation of MYC, as demonstrated in other ALK-activated tumor types." (PMID 29507657, 2018). "Further, activated MYC and RAS or the downstream RAS effector BRAF synergistically induce tumor development in vivo in various transgenic mouse tumor models." (PMID 30526305, 2018). "A similar phenomenon was previously shown for PVT1 (a gene in the vicinity of the MYC locus), since MYC/PVT1 co-amplification is required for efficient tumour formation in MMTV-Neu-driven tumours." (PMID 30082728, 2018).
tumor (continued). "The identification of convergence between KRAS signaling and NURD/MYC epigenetic reprogramming may inform evidence-based clinical trial development for metastatic lung cancer patients with activated KRAS mutations, or even potentially other tumor types with KRAS mutations." (PMID 30013058, 2018). "CD133 has crucial roles in tumor cell proliferation, colony formation, and the expression of stemness genes, including NANOG, OCT4, SOX2, and c-MYC." (PMID 30671168, 2018). "We also identify MYC, whose splicing and expression are highly dependent on SHQ1, as an important downstream effector mediating the tumor-supporting role of SHQ1." (PMID 30323192, 2018). "Membranous C-RAF and HA tag along with strong nuclear c-MYC and TTF-1 were detected in the tumor cells." (PMID 29464089, 2018). "Western blots exhibited major downregulation of c-MYC protein upon C-KRAS-esiRNA and C-KRAS/PIK3CA-esiRNA treatment, but not C-PIK3CA-esiRNA treatment in DLD1 tumors, whereas HT29 tumor reacted to treatment in a different manner." (PMID 30001368, 2018). "MiR-27a-5p knockdown in PC3 cells promoted cell growth, whereas miRNA forced expression in LNCaP and stable MYC-knockdown PC3 cells attenuated the malignant phenotype, suggesting a tumor suppressive role for miR-27a-5p." (PMID 29415999, 2018). "In tumour samples, we found that BFL1 expression was further elevated when compared to splenocytes from 2‐week‐old premalignant Eμ‐MYC/Vav‐BFL1 DT mice." (PMID 29498802, 2018). "The identification of potential tumor suppressor genes, PRDM1 and PTPRK, and pro-survival signaling via MYC and NF-KB are of particular importance as key events in ENKTL pathogenesis." (PMID 29966370, 2018). "c-MYC and NOXA levels are low in normal keratinocytes which provides a mechanism for tumour selectivity." (PMID 29755650, 2018). "Mice injected with T18 cells (MYC+AKT+BMI1), were euthanized at day 13, exhibited less pronounced splenomegaly and contained more modest numbers of tumor cells in the bone marrow, spleen and liver, accumulated tumor cells in the kidneys but not in the thymus." (PMID 29765548, 2018). "The overexpression of MYC and/or BCL2, doesn’t define a new tumor biology but rather, should be considered as an auxiliary prognostic signature that characterized a subset in DLBCL38." (PMID 29674626, 2018). "When c-MYC and HDAC8 expression is high, as in tumor cells, then the levels of suppressor miRNAs will be lower; conversely, when c-MYC and HDAC8 expression is low, at basal levels, then suppressor miRNA levels will be higher." (PMID 30237861, 2018). "There was a positive relationship between SLC7A5 and MYC, mTOR and ATF4 (p < 0.001) and the positive relationship between MYC, HIF2A and SLC7A5 was only observed in luminal B tumours (p = 0.01 and p < 0.001, respectively)." (PMID 29566741, 2018). "Like other oncogenes, activated MYC and RAS trigger intrinsic tumor suppressor mechanisms that limit their tumorigenic potentials." (PMID 30526305, 2018). "Tumor tissues derived from RIF1 knockdown H1299 cells exhibited decreased positivity for β-catenin and MYC compared with the control groups, indicating that RIF1 promoted Wnt/β-catenin signaling in the mouse model." (PMID 30237512, 2018). "Further, these studies showed that MYC inactivation restored RAS/BRAF-induced senescence, indicating that continuous MYC signaling is necessary for RAS/BRAF-induced tumorigenesis and tumor progression." (PMID 30526305, 2018). "MYC and TERT genes were also affected by focal gains in 8q and 5p observed in 55% and 40% of the tumours respectively." (PMID 29416628, 2018). "DH-My6 is a new well-validated MYC/BCL6 DHL cell line that will provide a useful model for studies of the pathogenesis and therapeutics for the less common DHL tumor type." (PMID 30323893, 2018). "Our data point to a novel role for calcium in supporting tumour cell viability and clarify the synthetic lethal interaction between NUAK1 and MYC." (PMID 29106388, 2018).